C8orf34 (chromosome 8 open reading frame 34)
Synonyms: vest-1; VEST1
Tractability: No criterion of Open Targets' tractability assessment is met for any kind of drug.
Safety:
Unwanted effects reported when the protein is acted on. In parentheses: how it was acted on, where the effect was seen, and who reports it.
Diarrhea (source: ClinPGx)
Gene: Protein-coding gene on chromosome 8 (68,330,669 to 68,819,023, forward strand). Ensembl gene ENSG00000165084.
Subcellular location (Human Protein Atlas): Nucleoli; Nucleoplasm; Golgi apparatus
Genetic constraint (gnomAD): Loss-of-function variants: 37 observed, 44.1 expected, observed/expected ratio (o/e) 0.84, 90% interval 0.64 to 1.1. The upper end of that interval is the gene's LOEUF score, 1.1, which puts it in group 4 of 6, group 1 being the genes least tolerant of losing a copy. Missense variants: 524 observed, 529.81 expected, observed/expected ratio (o/e) 0.99, 90% interval 0.92 to 1.06. Synonymous variants: 202 observed, 197.71 expected, observed/expected ratio (o/e) 1.02, 90% interval 0.91 to 1.15.
Homologues: Orthologues: chimpanzee C8H8orf34 (99% identical), macaque C8H8orf34 (98% identical), dog C8orf34 (77% identical), mouse A830018L16Rik (76% identical), pig C8orf34 (75% identical), rat C5h8orf34 (75% identical), rabbit C8orf34 (73% identical), tropical clawed frog c6h8orf34 (59% identical), zebrafish C24H8orf34 (54% identical).
Diseases named in the same sentence as C8orf34 in open-access papers:
C8orf34 is named in the same sentence as 5 diseases in open-access papers, as found by Europe PMC text mining. Sharing a sentence is not in itself a finding about the gene and the disease. The quoted sentences say what the papers report.
osteoarthritis (2 papers, 2021 to 2023). A noninflammatory degenerative joint disease occurring chiefly in older persons, characterized by degeneration of the articular cartilage, hypertrophy of bone at the margins and changes in the synovial membrane. "rs10282983 resides in an intron of C8orf34, which has been associated with waist-to-hip ratio and heel bone mineral density, both risk factors for osteoarthritis." (PMID 34450027, 2021).
vertebral disc disease (1 paper, 2023). "There is little known about C8orf34 regulation of joint tissues such as cartilage but it has been implicated in vertebral disc disease." (PMID 37619450, 2023).
C8orf34 also shares sentences with these, for which no sentence is quoted: breast carcinoma (1 paper); lumbar disc degeneration (1); tumour (1).